STAT3 (signal transducer and activator of transcription 3)
Diseases named in the same sentence as STAT3 in open-access papers (continued):
Sharing a sentence is not in itself a finding about the gene and the disease.
breast cancer (continued). "And the crosstalk between β-catenin and STAT3 signaling pathways has been reported in breast cancer stem cells." (PMID 32887217, 2020). "A previous study reported that H19 can competitively bind miR-93-5p to upregulate STAT3 and promote proliferation, migration, and invasion in breast cancer." (PMID 33318294, 2020). "Studies found that C3G inhibited breast cancer-induced angiogenesis via attenuating the signal transducer and activator of the transcription 3 (STAT3)/VEGF pathway." (PMID 32509879, 2020). "Considering the stem cell origin of breast cancer the role of STAT3 in normal stem cells cannot be overstated due to the role of the JAK-STAT3 pathway in cellular transformation." (PMID 32331320, 2020). "Constitutive activation of STAT3 has been observed in various tumors including lung cancer, breast cancer, prostate cancer, brain tumor, head and neck squamous cell carcinoma, and colon cancer." (PMID 32150979, 2020). "In studying the relationship between STAT3 and CSCs, Polyak and colleagues found that the IL-6/JAK2/Stat3 pathway is preferentially active in CD44+CD24− stem-enriched breast cancer cells, where it is required for their growth." (PMID 32391382, 2020). "Recent clinical and preclinical data indicate the involvement of overexpressed and constitutively activated STAT3 in the progression, proliferation, metastasis and chemoresistance of breast cancer." (PMID 32111215, 2020). "To sum up, we demonstrated for the first time the involvement of miR-337-3p and its target gene STAT3 in regulating EMT program of breast cancer under chronic stress in vivo and in vitro." (PMID 32934214, 2020). "In breast cancer, this phenotype is presumably induced by activation of STAT3, which strongly predicts the presence of WF." (PMID 32488850, 2020). "When the authors silenced STAT3 in breast cancer cells and co-cultured them with fresh blood-derived DCs, they found that the treatment strongly synergized CD24 and HER2 downregulation in the cancerous cells." (PMID 33322132, 2020). "While there has not been a comprehensive comparison of the downstream pathways activated by each ligand in breast cancer, many mechanistic studies have identified STAT3 as the key downstream mediator of IL-6 and OSM tumor-promoting effects." (PMID 32023849, 2020). "High levels of IL-10 have been reported to be responsible for drug resistance to breast cancer, in which the blockade of this cytokine resulted in diminished STAT3 activation and a decrease in Bcl-2 mRNA expression, and consequently the induction of apoptosis." (PMID 32244885, 2020). "Further, the expression and promoter activity of BST2 are also controlled by signal transducer and activator of transcription 3 (STAT3) in tamoxifen-resistant breast cancer cells." (PMID 31957537, 2020). "The Stat3-sufficient CD103+ cDC1 vaccine restrained bilateral mammary tumor growth, consistent with our prior observations in murine melanoma and osteosarcoma models." (PMID 31947933, 2020). "We then analyzed the expressions of PLSCR1, STAT3, and phosphorylated STAT3 (p-STAT3) in breast cancer cell lines and observed that PLSCR1 expression positively correlated with p-STAT3 expression." (PMID 32292520, 2020). "Firstly, they found that upon EGF stimulation, the STAT3/Sox-2 pathway is strongly upregulated in breast cancer cells, heading to uncontrolled cell proliferation, chemoresistance, maintenance of cancer cell stemness, and metastasis." (PMID 33322132, 2020). "An antagonist of Bcl-2 family proteins, Sabutoclax, downregulates survivin through IL-6/Stat3 signaling pathway, to improve chemosensitivity in breast cancer CSCs." (PMID 32691369, 2020).
breast cancer (continued). "Nicotine suppressed chemotherapeutic-induced apoptosis of breast cancer cells in vitro, via the signaling cascade involving STAT3, galectine-3, and a nicotinic acetylcholine receptor." (PMID 33053866, 2020). "Another phase I/II clinical trial of breast cancer involves Imx-110, a nanoparticle encapsulating the STAT3/NF-κB/poly-tyrosine kinase inhibitor and doxorubicin (NCT03382340)." (PMID 33266219, 2020). "Growing experimental evidence demonstrates that Signal Transducer and Activator of Transcription 3 (STAT3) is constitutively activated in a range of human cancers including breast cancer." (PMID 32503225, 2020). "The Si-STAT3 transfection also reduced the percentage of CD206+ or CD163+ THP-1 derived macrophages after the co-culture with linc00514-OVE breast cancer cells." (PMID 32943090, 2020). "On a functional level, STAT3 signaling has been reported to promote angiogenesis in human pancreatic, lung, and breast cancers and we have previously shown that STAT3 is a critical regulator of the pro-angiogenic functions of myeloid cells in mice." (PMID 33335857, 2020). "Our data suggest that PAA is useful for breast cancer treatment and the Stat3/IL-6 signal as a marker for CSCs targeting." (PMID 33202749, 2020). "Our previous reports that MKL-1 and STAT3 synergistically promote breast cancer cell migration and via hypermethylating BRSM1." (PMID 32646440, 2020). "STAT3 activation (phosphorylated STAT3 (pSTAT3)) increases the permeability of the lysosomal membrane and promotes cell survival in erastin-induced ferroptosis in breast cancer cells." (PMID 33014271, 2020). "Resistin promotes the growth and aggressiveness of breast cancer cells through STAT3 activation, indicating a potential role of resistin, IL-6 and STAT3 in breast cancer racial disparity in AA women." (PMID 32824813, 2020). "The other compound carnosol inhibits the migration and tumor growth via ROS-dependent proteasome degradation of STAT3 in several breast cancer cell lines." (PMID 32085594, 2020). "With our results, we cannot give a clear answer yet, because STAT3 signaling is highly inter-connected with other signals while participating in breast cancer progression, EMT, and the maintenance of CSC characteristics." (PMID 32326231, 2020). "Our findings indicated that overexpression of linc00514 promotes proliferation and invasion of breast cancer cells and M2 polarization of macrophages via reducing STAT3 expression." (PMID 32943090, 2020). "Recently, JAK1/STAT3 signaling was shown to be essential in breast metastasis, where STAT3 was identified as the crucial mediator of breast cancer migration upon upstream JAK activation." (PMID 33266219, 2020). "Increasing evidence indicates that the STAT3 pathway plays an important role in breast cancer metastasis, and several lncRNAs (e.g., HOTAIR and Lnc-BM) participate in this process." (PMID 32929060, 2020). "On the contrary, the ectopic expression of STAT3 elevated the IKKα expression level in human breast cancer MCF7 cells, lending further support to the notion that STAT3 up-regulates IKKα expression." (PMID 33396715, 2020). "Decreased GM-CSF and TSLP resulted in the mute of STAT3/β-catenin signaling and the suppression of breast cancer progression." (PMID 32887217, 2020). "Breast cancer cells highly active in STAT3 activity display increased dependency on autophagy for their survival." (PMID 32878084, 2020). "Signaling pathway studies demonstrated that PP and PL inhibit STAT3 activation and regulate apoptosis-related proteins in breast cancer cells." (PMID 31948057, 2020). "STAT3 is activated in breast cancer, and increased phosphorylation of the tyrosine 705 (Y705) site in STAT3 has been observed in tamoxifen-resistant MCF7/TAM cells." (PMID 33585187, 2020). "In both MCF7 and MDA-MB-231 breast cancer cell lines, 27-HC increased ROS production that led to increased migration of the cells via STAT3/VEGF signaling." (PMID 33604295, 2020).
breast cancer (continued). "Mechanistically, overexpression of linc00514 stimulated IL-6 and IL-4 secretion of breast cancer cells via STAT3/Jagged1 axis, and promoted monocyte polarization into M2-like macrophages and increase the tumor progression." (PMID 32943090, 2020). "STAT3 inhibition significantly inhibits tumor growth and sensitizes breast cancer cells to trastuzumab." (PMID 32872659, 2020). "3D cultures established from HCC1954 breast cancer cells treated with a small molecule Rac1 inhibitor had reduced pSer727 STAT3 levels and inhibited invasion." (PMID 32915198, 2020). "Taken together, blocking of STAT3 activation by combination of PP and PL was proven to be a mechanism of selective killing of breast cancer cells." (PMID 31948057, 2020). "STAT3 acts as a transcriptional activator in breast cancer, which regulates several target oncogenes and affects breast cancer progression, proliferation, apoptosis, metastasis and chemoresistance." (PMID 32111215, 2020). "As formerly mentioned, the Nar-Cpm combination was even more effective in the suppression of STAT3 phosphorylation than either compound alone, further proving its potential as a novel chemotherapeutic regimen for breast cancer treatment." (PMID 33680016, 2020). "Whereas leptin, an adipokine with a central role in obesity, induced JAK2/STAT3 signalling, leading to the promotion of breast cancer stem cell (CSC) survival and self-renewal." (PMID 32731620, 2020). "In breast cancer, hGH is capable of increasing the levels of the miR-183-96-182 cluster members via transcription factors, such as signal transducer and activator of transcription 3 (STAT3) and STAT5." (PMID 33066509, 2020). "Recent studies verified that abnormal activation of STAT3 signalling mediates cisplatin sensitivity in several cancers, such as breast cancer, OSCC, oesophageal squamous cell carcinoma and ovarian cancer and lung cancer." (PMID 32661236, 2020). "The in vivo experiments showed that the tumor volumes of mouse primary breast cancer were obviously smaller after the subcutaneous injection of the 4 T1 cells which were transfected with STAT3 siRNAs (Si-STAT3) or JAG1 siRNAs (Si-JAG1)." (PMID 32943090, 2020). "We found IL-22 stimulated proliferation of breast cancer cells in a signal transducer and activator of transcription 3 (STAT3)-dependent manner." (PMID 32649314, 2020). "This is strikingly consistent with our mechanistic model that S1P is persistent following STAT3 activation, chronic inflammation and development and progression of colon cancer as well as breast cancer." (PMID 32933189, 2020). "Another inhibitor is S3I-20, which blocks the STAT-3 DNA binding, promotesapoptosis, and inhibits growth in human breast cancer." (PMID 32167126, 2020). "CBD was shown to reduce STAT3 levels in colorectal cancers, prostate cancers, hepatocellular carcinoma, breast cancers, leukemia and lymphomas." (PMID 33143283, 2020). "This prompted us to more systematically explore the interplay between STAT3 and IKKα and its implications for the growth and progression of breast cancer cells." (PMID 33396715, 2020). "As with breast cancer, chemical Rac1 inhibition impedes STAT3 activation and blocks epithelial-mesenchymal transition (EMT) in CRC." (PMID 32915198, 2020). "Inhibition of STAT3 has also been shown to reverse the radioresistant phenotype in breast cancer cells." (PMID 32326381, 2020). "Since IL-6 exerts its influence on breast cancer cells via JAK2/STAT3 pathway, the inhibitory effect of Nar-Cpm combination on IL-6 influence further proves its ability to target JAK2/STAT3 signaling pathway." (PMID 33680016, 2020). "Because of its complexity and wide regulation of breast cancer cells, STAT3 is an interesting target candidate to treat in TNBC." (PMID 33138097, 2020). "The IL‐6/JAK/STAT3 pathway modulates the expressions of several genes involved in the proliferation, survival, and transformation of breast cancer cells." (PMID 33133558, 2020).
breast cancer (continued). "In breast cancer cells both ATX and LPA are associated with mobility and invasive capacity via the JAK/STAT3 pathway or PI3K/MAPK pathways." (PMID 33339340, 2020). "They found that FBP1 inhibits STAT3-dependent PD-L1 transcription, a finding that is consistent with our discovery in breast cancer." (PMID 32754266, 2020). "There is a plethora of evidence that leptin induces cell migration and invasion in breast cancer via JAK/STAT3 signaling." (PMID 33339340, 2020). "Mammary adipocytes also secrete leptin, activating the JAK/STAT3 signalling pathway in breast cancer cells, resulting in the upregulation of the CPT1B gene and FAO." (PMID 32731620, 2020). "Consistent with other findings that miR-34a significantly increased with the treatment of stattic (a small-molecule inhibitor of STAT3), we found that depletion of STAT3 markedly attenuated the leptin-induced suppression of miR-34a in breast cancer cells." (PMID 33371368, 2020). "Both IKKα and STAT3 were overexpressed in human breast cancer tissues compared to their normal counterparts." (PMID 33396715, 2020). "STAT3 is up-regulated in dormant tumor cells and was one of only six genes that was highly expressed in ER+ breast cancer cell lines with higher dormancy scores." (PMID 32023849, 2020). "Mitochondrial-targeted expression of mutant S727A STAT3 attenuates tumor growth and the metastatic ability of murine breast cancer (4T1) cells, which correlates with the reduction of complex I activity under hypoxia and leads to enhanced ROS production." (PMID 33003453, 2020). "Our results agree with the of previous findings on hepatocellular carcinoma and breast cancer showing that STAT3 activation contribute to the adriamycin resistance." (PMID 32461377, 2020). "Ruxolitinib, an FDA approved JAK1/2 inhibitor was found to attenuate STAT3 phosphorylation and reduce tumor growth in tamoxifen resistant breast cancer cells and is currently under clinical investigation (NCT02876302, NCT02066532, NCT03012230)." (PMID 33266219, 2020). "In the interplay between CSCs and TAMs, a putative role for the signal transducer and activator of transcription 3 (STAT3) pathway has been demonstrated in breast cancer models via a novel paracrine EGFR/Stat3/Sox-2 axis." (PMID 32630659, 2020). "It was found that β-caryophyllene oxide decreased the constitutive STAT3 activation in multiple myeloma, prostate, and breast cancer cells, and has a critical concentration- and time-dependent response in multiple myeloma cells." (PMID 32545187, 2020). "It appears that lovastatin‐induced survivin reduction also attributes to STAT3 inactivation in breast cancer cells." (PMID 31821701, 2020). "It has also been reported that the STAT3 inhibitor, pyrimethamine, displays anti-cancer and immune stimulatory effects in murine models of breast cancer." (PMID 32248842, 2020). "For example, persistent activation of STAT3 can resist apoptosis in human myeloma cells, fibroblasts, breast cancer, and gastric cancer." (PMID 33371351, 2020). "In breast cancer, MDSCs were shown to enhance the stem-like qualities of tumor cells by secretion of IL-6 and nitric oxide (NO) in a STAT3-dependent manner." (PMID 32117287, 2020). "Considering the regulatory role of STAT3 in breast cancer drug resistance and tumorigenesis, the exploration of new STAT3 inhibitors will assist the development new STAT3-targeted anti-cancer therapies for breast cancer." (PMID 32503225, 2020). "As shown by western blotting assays, STAT3 was activated in lncRNA LOC645166-overexpressing breast cancer cells and was suppressed in lncRNA LOC645166-silencing breast cancer cells under ADR treatment." (PMID 32461377, 2020). "In this study, we showed IL-22 exerted a proliferative effect on breast cancer cells in a STAT3-dependent manner." (PMID 32649314, 2020). "Noticeably, constitutive STAT3 activity is frequently found in triple negative breast cancers, and in more than 40% of all breast cancers." (PMID 33371351, 2020).
breast cancer (continued). "The inhibition of cDC1 development by breast cancers is due to their production of G-CSF, a STAT3-activating cytokine; consistent with these prior studies, we found PyMT tumor cells secrete G-CSF in culture." (PMID 31947933, 2020). "While, arctigenin decreased the expression of GM-CSF and TSLP and muted STAT3/β-catenin signaling in breast cancer cells, resulting in inhibited self-renewal ability of BCSCs." (PMID 32887217, 2020). "This review aims to explore the mechanism of STAT3 in breast cancer development and summarize the latest advancements made." (PMID 32111215, 2020). "Numerous signaling pathways, including MAPK, PI3K, STAT3, Wnt, Hedgehog, and Notch, amongst others, play a critical role in maintaining cell plasticity in breast cancer." (PMID 32391382, 2020). "STAT3 is centrally important for the maintenance of CD44+/CD24- CSCs in breast cancer, suppression of genes involved in cell proliferation correspondingly reduce STAT3 activation." (PMID 32754274, 2020). "AG490 is a tyrosine kinase inhibitor that inhibits the Jak2 pathway in breast cancer cells in vitro by decreasing the phosphorylation of Stat3." (PMID 33019728, 2020). "Here, we report overexpression and co-localization of IKKα and STAT3 in human breast cancer tissues as well as in human breast cancer cells, which promotes breast cancer promotion and progression." (PMID 33396715, 2020). "Mitochondrial STAT3 phosphorylation enhances growth and invasion of murine 4T1 breast cancer cells by increasing complex I coupling system and reducing ROS production." (PMID 33003453, 2020). "PL was identified as a direct STAT3 inhibitor with potent activity against breast cancer, while the role of PP to STAT3 regulation in breast cancer has not yet been reported." (PMID 31948057, 2020). "The upregulation of IL-6/STAT3/ROS can lead to the transcription of genes involved in breast cancer progression, as well as an augmentation in inflammation and generation of breast cancer stem cells (BCSCs)." (PMID 33138097, 2020). "Another recently described STAT-3 binding intrabody suppresses the function of phosphorylated STAT-3 and distinctly reduces cell proliferation in vitro and breast cancer growth in mouse xenografts." (PMID 33371447, 2020). "For example, high expression of MRE11, a core protein of the MRN (MRE11/RAD50/NBS1) repair complex, enhances breast cancer cell proliferation and invasion and promotes DNA repair through STAT3." (PMID 32872659, 2020). "The administration of NOB restricts the angiogenesis, migration, and proliferation of breast cancer cells via inhibition of the CD36/STAT3/NF-κB axis." (PMID 32380783, 2020). "Interactions between the NOTCH and STAT3 signaling pathways of MDSCs and CSCs play a crucial role in promoting and maintaining breast cancer stemness and consequent breast cancer progression." (PMID 33091036, 2020). "The immunofluorescence staining revealed that IKKα co-expressed and co-localized with STAT3 in tumors of human breast cancer patients." (PMID 33396715, 2020). "The recruited macrophages secreted IL-6 and oncostatin M, which activated the Lnc-BM/JAK2/STAT3 pathway in breast cancer cells." (PMID 32083005, 2020). "The siRNA-mediated STAT3 knockdown or JAG1 knockdown markedly inhibited the invasion of breast cancer cells." (PMID 32943090, 2020). "Breast cancer progression is promoted further by leptin stimulated STAT3 mediated FAO in CD8+ T effector cells." (PMID 32331320, 2020). "This study reflects that PSD-A induces apoptosis and autophagy and inhibits STAT3 activation in breast cancer cell lines." (PMID 33013353, 2020). "There is evidence showing that STAT3 activation is dependent on Ca2+ signal in breast cancer cells, and phosphorylation of STAT3 at Tyr705 by EGF can be substantially inhibited upon intracellular Ca2+ chelation." (PMID 32517717, 2020). "In this study, we determined that PSD-A is capable of inhibiting EGF-induced STAT3 activation in breast cancer cells." (PMID 33013353, 2020).